POM121L9P (POM121 transmembrane nucleoporin like 9, pseudogene )
Synonyms: DKFZP434P211; UNQ2565
Gene: Long non-coding RNA gene on chromosome 22 (24,247,862 to 24,265,525, forward strand). Ensembl gene ENSG00000290696.
Diseases named in the same sentence as POM121L9P in open-access papers:
POM121L9P is named in the same sentence as 1 disease in open-access papers, as found by Europe PMC text mining. Sharing a sentence is not in itself a finding about the gene and the disease. The quoted sentences say what the papers report.
clear cell carcinomas (1 paper, 2021). "By global mRNA microarray profiling in a total of 196 epithelial OC patients (161 serous, 15 endometrioid, 11 mucinous, and 9 clear cell carcinomas), we found four candidates—HSPA1A, CD99, RAB3A and POM121L9P, which associated with OS and poor clinicopathological features." (PMID 33686173, 2021).